IL1B (interleukin 1 beta)
Diseases named in the same sentence as IL1B in open-access papers (continued):
Sharing a sentence is not in itself a finding about the gene and the disease.
tumor (continued). "Tumour cells attracted PMN more so than did HMVEC stimulated with IL-1β." (PMID 20169105, 2009). "If unopposed, massive release of IL-6 under the stimulation by IL-1β might accelerate tumour progression to high stage malignancy by paracrine proliferative action on IL-6-responsive, i.e., still differentiated cells." (PMID 18205904, 2008). "Furthermore, blockage of the chemokine receptor CXCR2 inhibited tumor growth in vivo indicating that a functional murine IL-8 homologue contributes to IL-1β-mediated progression of disease." (PMID 18801189, 2008). "However, IL-6 is highly abundant in undifferentiated tumour cells and is effectively stimulated by IL-1β." (PMID 18205904, 2008). "In fact, enhanced tumor metastasis and angiogenesis has been observed under the influence of IL-1β." (PMID 18801189, 2008). "However, tumour tissue IL-1β protein levels were positively correlated with serum CRP concentrations (P=0.05, r=0.31; linear regression)." (PMID 17088911, 2006). "However, cytokine protein concentrations were significantly elevated in the tumour tissue: IL-1β 136 pg mg−1 of total protein (IQR 41–425), P=0.007; IL-6 3 pg mg−1 (IQR 0–46), P<0.05; IL-8 56 pg mg−1 (IQR 23–159), P=0.007; TNF-α 7 pg mg−1 (IQR 1–26), P<0.05." (PMID 17088911, 2006). "Cancer cells directly produce IL-1 or can induce cells within the tumor microenvironment to do so; studies have documented constitutive IL-1β protein production in human and animal cancer cell lines including sarcomas and ovarian and transitional cell carcinomas." (PMID 17096856, 2006). "Furthermore, IL-1β performs a synergistic role in potentiating natural killer cell and macrophage-mediated tumour lysis." (PMID 11986770, 2002). "This may reflect the role of IL-1b in inducing an acute phase protein response and cachexia in cancer or may be related to changes in tumour phenotye." (PMID 11076651, 2000). "A chimeric IL-6/IL-1β fusokine was engineered to test the hypothesis that enforced co-engagement of IL-6 and IL-1β signaling pathways would confer a gain-of-function phenotype in T cells and promote robust anti-tumor immunity." (PMID 42146708, 2026). "For example, tumor-derived extracellular vesicles from human squamous head and neck cancer and lung adenocarcinoma cell lines can interact with primary monocytes and induce their activated phenotype, which is characterized by the secretion of pro-inflammatory IL-1β and TNF-α." (PMID 40427136, 2025). "Furthermore, the conditioned medium from these M1-polarized macrophages significantly suppressed the expression of PD-L1, a key factor of immunosuppressive tumor microenvironment, which can be prevented by depleting IL-1β in macrophages (CM-THP1-shIL1β-CM-GC-EF1a-ALDH3A2)." (PMID 41444219, 2025). "Therefore, this study investigated the protein expression of NLRP3, ASC, caspase‐1, IL‐1B, IL‐18, IL‐1RA, and IL‐18BP on tumor cells by utilizing multiplexed immunohistochemistry on PDAC and IPMN samples, examining their association with pathological features and prognoses." (PMID 39969214, 2025). "Therefore, we hypothesize that anti-tumor immune response to the combination of anti-IL-1β and anti-PD-1 antibodies is context-dependent and would be affected by the stromal heterogeneity in PDAC." (PMID 39948655, 2025). "This properdin deficiency results in low levels of IL-1b mRNA and higher levels of arginase-1, monocyte chemotactic protein-1 (MCP-1), and IL-10 mRNAs, suggesting that a properdin-deficient tumor microenvironment may induce a profile of M2 macrophages with pro-tumoral activity." (PMID 40370471, 2025). "Likewise, the correlation with PD-L1 expression suggests that IL-1β may promote an immunosuppressive TME by driving PD-L1 upregulation on tumor or immune cells, thereby facilitating immune evasion." (PMID 40940992, 2025). "However, it has been shown that IL-1β-deficiency does not affect tumor formation in the AOM/DSS model." (PMID 40767963, 2025).
tumor (continued). "Furthermore, mobilized N1-TANs can differentiate into antigen-presenting cells by expressing MHC class I and class II molecular T cells and activate Th17, CD8 T, proliferating Τ, and NK cells in cytokine signaling pathways via IL1B, thereby amplifying anti-tumor immunity." (PMID 40360503, 2025). "We found that similarly to TEVs, the PD-L1 levels were higher in resistant cells and after IL-1β stimulation than the control cells, thus suggesting that TEVs and cancer cells, from which they are released, may synergistically contribute to tumor immune evasion." (PMID 40725070, 2025). "Besides, it has been confirmed that blocking IL-1β could enhance the anti-tumor activity of anti-PD-1 immunotherapy, underscoring its significance as a therapeutic target." (PMID 40604924, 2025). "A recent study revealed that IL-1β can regulate iron-sulfur cluster homeostasis by inducing the acetylation of the mitochondrial inner membrane protein nicotinamide nucleotide transhydrogenase, thereby inhibiting ferroptosis in tumor cells and mediating immunotherapy resistance." (PMID 40895546, 2025). "Here, we report on (i) the role of (IL-1β) in activating a signaling cascade that leads to proliferation and metastasis in glioblastoma cancer pathogenesis as well as (ii) the therapeutic role for IL-1 Receptor Antagonist (IL-1RA) and Tolcapone against untoward aspects of tumor pathogenesis." (PMID 40725140, 2025). "IL-1β participates in a feedback loop in several human cancers, promoting tumor immune escape via increased PD-L1 expression, the secretion of macrophage-recruiting proteins, the acquisition of malignant characteristics by tumor cells, and worse patient prognosis." (PMID 41445746, 2025). "Additionally, release of LDH, IL-18, and IL-1β were detected in both serum and tumor samples." (PMID 41415273, 2025). "Therefore, we hypothesize that anti-tumor immune response to the combination of anti-IL-1β and anti-PD-1 antibodies is context-dependent and would be affected by the TME heterogeneity in PDAC." (PMID 39948655, 2025). "Similarly, fibulin-3 inhibition decreased IL-1β in the tumor cells but IL-1β in the host (mouse) was unchanged or increased, indicating additional cell sources for this proinflammatory cytokine in the tumor." (PMID 40844085, 2025). "To investigate how Nlrp3 deficiency affects the chitosan-stimulated tumor microenvironment (TME), we further analyze the percentages of immune cell populations in Nlrp3-/- mice compared with their WT counterparts, particularly neutrophils and monocytes responsible for IL-1β inflammation." (PMID 40860135, 2025). "Furthermore, the inhibition of IL-1B signaling enhanced cell death induced by cisplatin and irradiation, suggesting that IL-1B may play a crucial role in tumor behavior and treatment resistance." (PMID 40141426, 2025). "However, compared to IL-1β, the role of IL-18 in the tumor microenvironment is less defined." (PMID 40155968, 2025). "However, the influences of IL-1β on tumor cell themselves are often overlooked and remains largely unknown especially for tumor-derived IL-1β." (PMID 41145465, 2025). "However, the therapeutic effect of IL-1β inhibitors alone appears limited and may require combination with other immunotherapeutic approaches to enhance their anti-tumor activity." (PMID 40109347, 2025). "Depending on their subtype, TAMs can produce either pro-inflammatory cytokines (e.g., IL-1β and IL-6) or anti-inflammatory cytokines (e.g., IL-4 and IL-10), thereby modulating the cytokine profile and shifting the tumor microenvironment toward either tumor suppression or tumor promotion." (PMID 40308575, 2025). "IL-1β may promote tumorigenesis and tumor proliferation through different molecular mechanisms." (PMID 40244135, 2025). "Furthermore, biologically active IL-1β is required for tumor invasiveness and angiogenesis." (PMID 39796680, 2024).
tumor (continued). "Finally, due to the association of PANX1 channel function and the pro‐inflammatory and tumor promoter cytokine: interleukin‐1β (IL‐1β), we investigated whether the IL‐1β expression was affected within the TME of BPC Panx1‐deficient mice." (PMID 38327091, 2024). "However, this hypothesis must be confirmed in a large cohort with the support of a genetic analysis, in order to determine whether the high expression of IL-1β could be considered a marker of advanced disease and/or a better host anti-tumor response." (PMID 38397123, 2024). "Consequently, inhibiting the production of IL-1β by MDSCs may represent an important therapeutic strategy to prevent tumor growth." (PMID 39294673, 2024). "Moreover, LPS-induced activation of TLR4 promotes inflammation by stimulating the production and release of pro-inflammatory cytokines (such as TNF-α, IL-1β, and IL-6), thereby indirectly contributing to neoplasia through maintaining proinflammatory microenvironment." (PMID 39328278, 2024). "Numerous studies have demonstrated the crucial role of IL-1β in T cell polarization, acute inflammation, and adaptive anti-tumor responses; whereas, in chronic inflammatory processes, the IL-1β produced by tumor-infiltrating macrophages may play a supportive role in tumor development." (PMID 39075190, 2024). "However, the influence of IL-1β and IL-18 on tumorigenesis is still debatable and may vary depending on the tumor context." (PMID 38523155, 2024). "Neutrophils and AMs likely form the first-line response to A. temperans instillation and secretion of IL-1β and IL-23 from these cells was previously found to be critical for activation of γδ T17 cells in KP mice, which then recruited additional neutrophils to the tumor site." (PMID 38570533, 2024). "This shows that IL-1β could promote both the onset and the progression of tumor cells." (PMID 39451241, 2024). "Moreover, SPP1 + Mac-derived TNF-α and IL-1β can promote the expression of OPN in both tumor cells and adjacent normal macrophages in turn, which may transform into SPP1 + Macs." (PMID 39726047, 2024). "Moreover, a contingency analysis confirmed the significant association of combined expressions of ‘Ki-67 and IL-1β’, as well as a Ki-67/IL-1 ratio with a high tumor grade (p = 0.02 and p = 0.01, respectively—not shown)." (PMID 38397123, 2024). "Inflammatory factors such as IL-18 may stimulate Th2 responses and angiogenesis, leading to enhanced tumor migration and invasion, and IL-1β can attract monocytes in the TME and operate as a master cytokine in cancer growth, as well as dampen T cell responses in the TME." (PMID 38890642, 2024). "Moreover, various cytokines such as IL-1β and IL-6, known to promote tumor development and progression, are found in the tumor ECM, along with the immune activator TNF-α, which is linked to anti-tumor immune response." (PMID 38955827, 2024). "Notably, active IL-1β was reported to be important for eliciting antitumor immunity during radiation therapy as inflammasome deficient mice failed to mediate tumor destruction." (PMID 38391959, 2024). "However, as the tumor metastasis evolves, these neutrophils transition to a pro-cancer phenotype characterized by a decline in IL-1β and heightened expression of MMP-9 expression, along with curtailed T cell activation, decreased production of cytokines, and diminished interferon γ signaling." (PMID 38243240, 2024). "In addition, our results suggest that HDM predominantly activates the NLRP3 inflammasome in macrophages, but we cannot exclude that other cell types such as neutrophils and/or eosinophils also contribute to IL-1β secretion and to the tumor-promoting effect of HDM." (PMID 36670473, 2023). "In addition to the inflammatory markers and tumor markers, the pro-inflammatory cytokines, IL-1β and IL-6, and TNF-α serum detection could play an important role in diagnosis and also in prognosis, although their detection incurs increased costs." (PMID 38137862, 2023).
tumor (continued). "The inhibition of IL-1β may lead to the decreased release of dysregulated inflammatory cytokines, while simultaneous PD-1/PD-L1 inhibition targets T cells, overcoming their anti-tumor immunity." (PMID 37511306, 2023). "To test this hypothesis, we subcutaneously inoculated BALB/c mice with the control or Arf1‐ablated CT26 cells, and then administrated mice with anti‐IFNAR1 and anti‐IL‐1β antibodies or isotype control antibodies at day 0, 2, and 4 after tumor cell injection, respectively." (PMID 37786300, 2023). "Pharmacological inhibition of NLRP3 inflammasome in HNSCC mouse models significantly reduces the IL-1β production, which reduces MDSCs, regulatory T cells (Tregs) and tumor-associated macrophages (TAMs) but increases CD4 and CD8 T cells in tumors to improve anti-tumor immunity." (PMID 36742298, 2023). "Thus, it implies that anti-IL-1β treatment benefits anti-tumor therapy." (PMID 37932814, 2023). "However, the role of IL-1β in tumor biology remains controversial." (PMID 37819510, 2023). "However, when NLRP3 or IL-1β is silenced, the tumor-promoting effect is impaired." (PMID 37497237, 2023). "In kidney cancer, scRNA-seq and ST analysis of cells at the tumor-normal interface versus the tumor core revealed an epithelial-mesenchymal transition meta-program highly enriched at the tumor-normal interface that co-localizes with IL1B-expressing macrophages." (PMID 37806992, 2023). "Results showed that conditioned medium from FAP-over-expressed LX2 cells could decrease the expression of M1 markers like iNOS, TNF-α and IL-1β but increase the expression of M2 markers like IL-10 in macrophages as compared to NC group, transforming the macrophages into M2 pro-tumor phenotype." (PMID 37325617, 2023). "The authors posited that this may be because activation of inflammasomes and production of IL-1β could recruit myeloid-derived suppressor cells (MDSC) and tumor-associated macrophages to tumor tissues, creating a favorable microenvironment for tumor metastasis." (PMID 37020871, 2023). "IL-1β may also contribute to angiogenesis and invasiveness of the tumor." (PMID 36742298, 2023). "We also examined IL-1β and IFN-γ gene expression in individual patients and found that IL-1β gene expression in myeloid cells was significantly associated with tumor progression, whereas such an association was not apparent for IFN-γ gene expression in NK cells or T cells." (PMID 37441079, 2023). "Indeed, IL‐1β antibody or MCC950 treatment significantly delayed tumor progression." (PMID 38116060, 2023). "In addition, UM cells showed significantly lower levels of IL‐1β secretion compared with the CM cell line Hs294t (P < 0.05), which might indicate an even lower potential of UM to recruit immune cells to the tumor site." (PMID 36707938, 2023). "Lastly, high levels of IL-37 secreted by peripheral blood Tregs of individuals with melanoma reflect the secretion of TGFβ and other IL-1β mediators by the tumor, thus indicating it could be interpreted as a potential marker for immunosuppression induced by the tumor." (PMID 37298214, 2023). "We found that the tumor volumes were comparable between WT and Il1b–/– recipient mice at this early stage of tumor development, indicating that tumor initiation was not affected in Il1b–/– mice, but rather that reduced tumor growth in Il1b–/– mice is the driver of prolonged survival." (PMID 37733448, 2023). "Furthermore, the authors show that IL‐1β‐mediated anti‐inflammatory interventions can alleviate the formation of a pre‐metastatic niche in the lung induced by surgeries and reduce subsequent colonization of circulating tumor cells." (PMID 37585564, 2023). "Interestingly, UA could dose-dependently weaken the increased spleen weight in LLC tumor-bearing mice at concentrations within 200 mg/kg, and the cytokines IL-6, IL-1β, and TNF-α are produced by immune cells or tumor cells." (PMID 37190306, 2023).
tumor (continued). "Therefore, hyperactivated EGFR contributes to the tumor-promoting effect of IL-1β in OSCC." (PMID 37834377, 2023). "Activation of SRC in tumor-associated macrophages is induced by tumor-derived cytokines and chemokines (e.g., TNF, MIP, SDF-1), which amplify the production of inflammatory cytokines (e.g., TNF, IL1β, IL6) to reciprocally activate SRC in a feed-forward loop and promote PDAC progression." (PMID 37120696, 2023). "Similarly, inhibiting the IL-1β pathway with an IL-1 receptor antagonist (IL-1Ra) may play a crucial role in suppressing tumor growth." (PMID 38066523, 2023). "Moreover, PepO significantly switched TAM to the tumoricidal M1 macrophage as reflected by a reduction in the expression of M2 markers Arg-1, CD206, Fizz-1, Ym1 and IL-10 while increasing the expression of M1 markers iNOS, IL-12a and IL-1β and promoted apoptosis of the tumor cells." (PMID 37925462, 2023). "Additionally, CAFs aggravate tumor development by secreting IL-1β, IL-6, and IL-8." (PMID 37990331, 2023). "Besides IL-1β, myeloid cell-derived IL-18 also facilitates anti-tumor immunity." (PMID 36932407, 2023). "Interestingly, key factors known to induce immune evasion in tumor microenvironment, namely Foxp3 + (marker for T regulatory cells-Treg) and Il-17A were significantly increased in the esophagus of IL-1β transgenic mice compared to wild type littermates." (PMID 37543673, 2023). "Pyroptotic cells release a large number of immunogenic cellular contents including damage-associated molecular patterns (DAMPs) and inflammatory cytokines such as interleukin-1β (IL-1β) and IL-18 and trigger inflammation, which may remodel the tumor immune microenvironment (TME)." (PMID 37051536, 2023). "Therefore, IL-1β could be a potential target to modulate neutrophilic infiltration into the tumor upon radiation." (PMID 38067390, 2023). "Moreover, chemotherapy treatment of tumor cells (e.g., with oxaliplatin and anthracyclines) can cause tumor cells to release ATP, which is an activation signal for the NLRP3 inflammasome and the IL-1β/IL-1 receptor (IL1R) signaling axis in dendritic cells (DCs)." (PMID 37497237, 2023). "Therefore, therapies targeting the CXCLs/CXCR2 axis and/or IL-1β signaling may increase the RT-mediated innate response and immune-modulation through shaping tumor-infiltrating neutrophil activity in the TME." (PMID 38067390, 2023). "Thirdly, tumor-associated macrophages (TAMs) within the TME can become activated by cancer cells via an unspecified mechanism, presumably related to Snail stabilization and the epithelial-to-mesenchymal transition (EMT) that triggers the secretion of IL-1β and IL-6." (PMID 36613445, 2022). "In many tumours, IL-1β may increase tumour cell metastasis by promoting angiogenesis." (PMID 35902905, 2022). "Furthermore, the synergistic action of IL-1β inhibition with anti-PD-1 improves tumor death, which may have significant clinical application." (PMID 35086565, 2022). "Firstly, inhibiting IL1β prevents wnt activation of cancer stem cells in the bone, holding tumour cells in a dormant state in this organ which might explain why IL1β inhibition is more effective at inhibiting metastatic outgrowth than reducing the growth of overt metastases." (PMID 36230739, 2022). "Moreover, MDSCs, through tumor-derived IL1β, impair NK cell development and activity." (PMID 35954459, 2022). "Moreover, in a pancreatic cancer model, it was shown that cancer-cell-derived IL-1β and a high-fat diet could increase the number of pro-tumorigenic lipid-loaded TAMs, enabling tumor progression." (PMID 36551635, 2022). "Moreover, the researcher discovered that genipin could reduce the expression of iNOS and IL-1β in the M2-like TAMs to inhibit tumor growth." (PMID 36615387, 2022).